BRCA1 (BRCA1 DNA repair associated)
Diseases named in the same sentence as BRCA1 in open-access papers (continued):
Sharing a sentence is not in itself a finding about the gene and the disease.
breast cancer (continued). "However, the BRCA1 and BRCA2 PVs coinheritance, in the population-based Israeli national breast cancer cohort, was described in 2.2% of all carriers, and 17 double heterozygotes for CPGs were detected in a breast cancer cohort of people of Slavic ancestry which included 5391 patients." (PMID 38929805, 2024). "Additionally, there may be a connection between the breast cancer-related tumor suppressor genes BRCA1/BRCA2 and RIBAS, although the exact mechanism is not yet fully understood." (PMID 39451649, 2024). "Therefore, HRT should not be carried out in BRCA1/2-pV carriers after diagnosis of breast cancer." (PMID 39259360, 2024). "Furthermore, the expected-observed difference is in keeping with a recent study, where the survival of BRCA1 carriers breast cancer was nominally higher than survival of non-carriers in pathology- and treatment-adjusted analysis of patients with ER-negative breast cancer." (PMID 37173335, 2023). "Using both parental and shBrca1 knockdown MDA-MB-231 cells, we demonstrated that overexpression of FGFR2 could dramatically promote tumor cell growth and activate downstream targets, illustrating the oncogenic role of FGFR2 and its related signaling in breast cancers regardless of BRCA1 status." (PMID 37063417, 2023). "However, the exact rate of BRCA1/2 PV may be higher in patients with ER+/HER2- breast cancer, particularly because BRCA2 PV carriers frequently do not fully fill in personal or family testing criteria in approximately 50% of cases." (PMID 35158866, 2022). "Therefore, even if a negative result with BRCA1/2 genetic testing cannot rule out hereditary breast cancers, other genetic testing or multi-gene panels may be considered when the medical or family history strongly suggests hereditary cancers." (PMID 35191009, 2022). "Data from the U.S. suggest that mutations in the breast cancer susceptibility genes BRCA1 and BRCA2 may be more prevalent in African-American compared to non-Hispanic White women, while mutations in other breast cancer genes may be less common in African-Americans." (PMID 35012613, 2022). "In comparison to non-carriers, BRCA1/2 carriers were more likely to have early onset breast cancer (48% versus 28%, p = 0.05), to be premenopausal at the time of diagnosis (82% vs. 54%, p = 0.02), and to have family history of breast cancer (45% vs. 35%, p = 0.024)." (PMID 34206661, 2021). "To address this gap, we examined frequency and predictors of BRCA1/2 and multigene panel testing and assessed racial/ethnic differences in genetic testing frequency and results (pathogenic/likely pathogenic [P/LP], VUS, negative) among diverse women with early-onset breast cancer." (PMID 31802423, 2021). "In gene panel sequencing for breast cancer predisposition, CHEK2 is consistently found to have a high number of pathogenic variants, usually only surpassed by the number of pathogenic variants identified in BRCA1 and BRCA2 in most settings not involving selection by breast cancer subtype." (PMID 33803639, 2021). "The BRCA1 and BRCA2 mutations are characterized by lacking an important error-free DNA repair process of homologous recombinational repair for repairing single-strand breaks; therefore, these mutations significantly increase the risks of breast cancer and ovarian cancer." (PMID 33802424, 2021). "Nipple-sparing mastectomy (NSM) is a surgical procedure performed in patients with breast cancer without the involvement of the nipple-areolar complex (NAC), to improve the cosmetic outcome and quality of life in women with early breast cancer or germline BRCA1/2 mutation." (PMID 33967619, 2021). "Therefore, breast cancer from BRCA1 carriers is a type of premenopausal breast cancer and is associated with Triple-negative breast cancer (TNBC) which is defined as a subset of breast cancer with the lack of expression of estrogen receptor (ER), progesterone receptor (PR), and HER2." (PMID 33167385, 2020).
breast cancer (continued). "Furthermore, BRCA1 deficiency accelerated tumor growth along with GOT2 upregulation by its transcriptional activation (or derepression), which indicates that mCAT could act as a metabolic malignancy driver in the absence of BRCA1 or ZBRK1 in breast cancer." (PMID 32882966, 2020). "We performed whole exome sequencing (WES) in first-degree cousin pairs affected by hereditary BC negative at the BRCA1/2 (BReast CAncer gene 1/2) testing." (PMID 32906649, 2020). "Consistent with the subtyping in our clinical trial samples, few BRCA1 germline mutation related breast tumors in TCGA database are immunomodulatory (7% versus 21% of TNBC from non-carriers) and most BRCA2 germline mutation related breast cancers do not classify as TNBC (12 out of 15, 80%)." (PMID 32164626, 2020). "Therefore, the interaction between BRCA1 and GADD45 may play a role in breast cancer pathogenesis through the stimulation of NER, increasing the genomic stability, removing carcinogenic adducts, and the local active demethylation of genes important for cancer transformation." (PMID 32013256, 2020). "MCF7 cells depleted of PRMT1 or BRCA1 showed a significant decrease in Bcl-2 protein, but experiments in the presence of MG132, a proteasome inhibitor, and analysis of Bcl-2-mRNA indicated that BRCA1 and PRMT1 might differentially regulate Bcl-2 protein levels in breast cancer cells." (PMID 32764667, 2020). "Therefore, features of genomic instability such as that mediated by BRCA1- and BRCA2- deficiency in breast cancer were necessary, but not always sufficient, for yielding T cell-inflamed tumour microenvironment, and by extension, predicting clinical benefit from immunotherapy." (PMID 31022191, 2019). "In addition, breast cancer cells lacking BRCA1 expression were more sensitive to mTOR inhibition." (PMID 31771139, 2019). "In agreement with the previous studies, where BRCA1 mutations, which predispose to TNBC have been found to have increased ROS levels, our data shows increased ROS levels in all the TNBC cell lines studied in comparison to an ER+ breast cancer cell line or the non-tumorigenic cells." (PMID 31231612, 2019). "Notably, BRCA1-deficient breast cancers with PTEN mutation, but not BRCA1-deficient breast cancers without PTEN mutation, had significantly higher T cell-inflamed signature scores compared to BRCA-proficient breast cancers (P = 9.3 x 10−3 and 0.07, respectively)." (PMID 31022191, 2019). "However, it is not clear whether germline mutations in other breast cancer susceptibility genes also predispose to TNBC, or whether the BRCA1 and BRCA2 genes interact and cooperate with other genetic susceptibility genes to drive TNBC." (PMID 30909550, 2019). "In the estrogen-dependent BC cell lines ZR75-30 and ZR75-1, it was found that both ZNF423 and BRCA1 (Breast Cancer 1) could be induced by estradiol." (PMID 29867779, 2018). "When breast cancer cells are treated with radiotherapy, chemotherapy or PARP inhibitors, the resulting DNA damage could be still repaired through the activation of specific DNA repair genes, such as ATM, BRCA1/2, RAD51, DNA-PK etc., thus cells survive and continue to proliferate." (PMID 30234015, 2018). "There are significant discrepancies in clinical data regarding the nuclear/cytoplasmic distribution of BRCA1 in breast cancer and lack of knowledge regarding whether BRCA1 expression level or its nuclear localization is the primary contributing factor to breast cancer development and progression." (PMID 28863181, 2017). "Therefore, at least for BRCA1, the MLPA test should be considered for breast cancer patients with a family history of breast and/or ovarian cancer and additional personal factors such as bilateral breast cancer, young age at onset, and TNBC during the genetic counseling process." (PMID 28205045, 2017).
breast cancer (continued). "To experimentally define whether IRISOE drives the TNBC phenotype in breast cancer cells, we analyzed IRISOE association with the known criteria for TNBCs; namely lack of BRCA1 expression, enhanced basal-biomarkers, EMT-inducers, stemness-enforces expression, and TIC phenotype." (PMID 28052035, 2017). "However, more recent evidence suggests that breast cancer-risk reduction with RRSO may not be significant, particularly for BRCA1 carriers." (PMID 28320467, 2017). "However, in breast cancer cells, FRK suppresses cell proliferation by arresting cells in the G1 phase of the cell cycle; regulating PTEN protein stability and function; inhibiting EGFR signaling, and by regulating the stability and potentially the tumor suppressor function of BRCA1 protein." (PMID 29348886, 2017). "Thus, EMT promotion in triple-negative basal-like breast cancer cells that have BRCA1 dysfunction may be independent of GR." (PMID 26797644, 2016). "Conditional transgenic models of BRCA1 mutant breast cancers have not been used widely in preclinical trials except for the study of K14-Cre; BRCA1fl/fl mouse in testing the efficacy of Olaparib43 and Topotecan44, wherein BRCA1 5-14 exon floxed animals were used." (PMID 27220670, 2016). "However, we do not expect significant differences between BRCA1 and BRCA2 mutation carriers in choice of (risk reducing) breast surgery, since both groups probably received similar information about the risk of (contralateral) breast cancer." (PMID 25700605, 2015). "Meanwhile, the prevalence of BRCA1 methylation in Asians (OR = 4.03, 95%CI 1.07–15.18, P = 0.04) was higher than that in Caucasians (OR = 3.16, 95%CI 1.78–5.62, P < 0.001) and in Australians (OR = 3.27, 95%CI 1.37–7.84, P = 0.008) in breast cancers compared with non-cancer controls." (PMID 26643130, 2015). "Interestingly, there was a suggestion of an rs299290 association with ERα-negative breast cancer for BRCA2 mutation carriers, but in the opposite direction to that observed for BRCA1 mutation carriers: ERα-negative BRCA2 mutation carriers n = 434, per-allele HR = 0.83, 95% CI 0.70–0.97, p = 0.022." (PMID 25830658, 2015). "Moreover, BRCA1 is repeatedly absent or significantly decreased in sporadic breast cancer." (PMID 25268620, 2014). "We identified BRCA1/2 small mutations in 78 (35.3%) out of 221 familial breast cancer patients using direct sequencing, or mutation scanning including F-CSGE and dHPLC followed by direct sequencing, and identified BRCA1 LGRs in 3 (2.1%) out of 143 BRCA1/2 small mutation-negative patients using MLPA." (PMID 25176351, 2014). "Finally, Signature 3 is associated with inactivating mutations in BRCA1 and BRCA2 genes, indicating that abrogation of functional HR- and/or NHEJ-mediated repair contributes considerably to breast cancer development, even in patients not harbouring a germline mutation in either of these two genes." (PMID 24792170, 2014). "However, emerging data suggest that different tumors are likely to respond to DZNep in a heterogenous fashion —for example, estrogen receptor (ER)-negative breast cancers with low BRCA1 levels may be particularly DZNep-sensitive." (PMID 25225797, 2014).
breast cancer (continued). "We propose the presence of a strong correlation between aberrant methylation of BRCA1 promoter in WBC, regardless of its presence or absence in breast tissue, and breast cancer-related molecular changes, which may advocates the risk for developing breast cancer." (PMID 25403427, 2014). "To determine if SLX4 is involved in breast cancer susceptibility, we sequenced the entire SLX4 coding region in 738 (270 Jewish and 468 non-Jewish) breast cancer patients with 2 or more family members affected by breast cancer and no known BRCA1 or BRCA2 mutations." (PMID 23840564, 2013). "Importantly, it has been shown that BRCA1 (breast cancer early-onset 1) protein binding to PRC2 inhibits the binding of HOTAIR to the EZH2 component of PRC2, and abolishes HOTAIR-enhanced recruitment of PRC2 to its target HOX (homeobox) A9 gene promoter in human breast cancer cells and fibroblasts." (PMID 23875687, 2013). "While the risk for second primaries has been studied in BRCA1 or BRCA2 mutation carriers, preliminary data indicate that the risk of contralateral breast cancer is not significantly elevated in patients with familial breast cancer, who tested negative for BRCA1/2 mutations." (PMID 23216834, 2012). "However, it was not clear whether c-Myc could transcriptionally regulate BRCA1 expression through a cis-regulatory element, particularly in breast cancer cells." (PMID 21668996, 2011). "Moreover, a lack of HER-2 expression was observed in breast cancer tumours of BRCA1 carriers." (PMID 20961453, 2010). "More recently, evidence has been presented from several studies to suggest that heterozygous carriers of BRCA1 and BRCA2 mutations, and breast cancer patients without such alterations may be distinguished based on mRNA profiling of fibroblasts and lymphoblastoid cell-lines (LCLs)." (PMID 20174566, 2010). "Indeed, the positive effect of BRCA1 deficit on Xa XIST expression is demonstrated in vitro by BRCA1 silencing in XCI-type 2 (Xi negative/XIST positive) MCF7 breast cancer cell line, which leads to a significant increase of XIST levels and promoter demethylation." (PMID 19440381, 2009). "The ultimate aim of this experiment was to establish if gene expression profiles could distinguish between BRCA1 or BRCA2 pathogenic mutation carriers and familial breast cancer cases whose disease was not attributable to BRCA1 or BRCA2 mutations (BRCAX cases)." (PMID 18497862, 2008). "Thus, in contrast to other mouse mammary tumor models in which the genomic features allow pooling multiple original tumors for expansion in vivo to provide virtually unlimited starting material, Brca1 mammary tumors should be analyzed individually and not pooled." (PMID 18394172, 2008). "The two major breast cancer susceptibility genes, BRCA1 and BRCA2, have been shown to be involved in a significant proportion of families affected with breast and ovarian cancer, but it is clear that about 70% of familial breast cancer is not caused by mutations in these genes." (PMID 17760956, 2007). "Although the sample size for the analysis was sufficient, GT for BRCA1 and BRCA2 was not conducted for all breast cancer cases at the time of the study." (PMID 40323562, 2025). "Consistent DFS, BCSS, and OS results as in the entire cohort were observed between BRCA1 and BRCA2 carriers with hormone receptor–positive and hormone receptor–negative breast cancers." (PMID 39993249, 2025). "We used data on 3,046 BRCA1 and 3,264 BRCA2 PV carriers, and 2,857 non-carrier female relatives of PV carriers from the Epidemiological Study of Familial Breast Cancer (EMBRACE)." (PMID 40399999, 2025). "Most of the patients did not have any second primary breast cancer (92.7%—BRCA-negative; 92.9%—BRCA1 group; 81.8%—BRCA2 group)." (PMID 41002733, 2025). "In untreated cells from mammary tumors lacking full-length BRCA1, SIRT1 was significantly lower compared to the BRCA1-wild type, as well as in transgenic mice models." (PMID 40136510, 2025).
breast cancer (continued). "Another study on TNBC patients shows that BRCA1 genetic testing is appropriate for women who develop TNBC, regardless of family history of breast cancer or ovarian cancer." (PMID 41541272, 2025). "In both normal breast tissue and in breast cancer, methylation levels of the promoter regions of tumour suppressor genes such as BRCA1, BRCA2, and ESR1 were higher in both BRCA1/2 PV carriers than non-carriers." (PMID 39682099, 2024). "Moreover, the AUC that included the PRS and known breast cancer risk factors with or without BRCA1/2 mutations was significantly higher than that of the risk factors alone, suggesting the PRS may add additional predictive values in identifying breast cancer patients with an elevated risk of CBC." (PMID 38263039, 2024). "This study corroborates preclinical evidence that regardless of BRCA1 status, PARP inhibition radiosensitizes cancer cells including breast cancer cells across two distinct forms of radiotherapy, probably through unresolved DNA damage−21,31." (PMID 39730675, 2024). "Genetic differences of breast cancer by ER status were first characterized between BRCA1 and BRCA2-related tumors, with BRCA1-related tumors predominantly lacking ER expression." (PMID 38515142, 2024). "Carriers were further categorised into those who had a FDR with breast cancer (FH+; n = 78 for BRCA1 and n = 170 for BRCA2) and those who did not (FH-; n = 152 for BRCA1 and n = 441 for BRCA2)." (PMID 37936660, 2023). "In breast cancer, the increase in STING pathway activation was observed to be pronounced in BRCA1/2 mutant but not in BRCA1/2 wild-type tumours." (PMID 37582853, 2023). "We observed differences in receipt of a more intensive regimen among PV carriers vs noncarriers: BRCA1/2 PV carriers with HR-positive, HER2-negative breast cancer received more intensive regimens, particularly as defined by platinum use." (PMID 35723570, 2022). "In addition, a BRCA1-mutation is associated with the more aggressive molecular phenotype of FBC (e.g., triple receptor–negative, oestrogen receptor (ER) negative, progesterone receptor (PR) negative, and HER2 negative), earlier disease onset, and family history of breast cancer." (PMID 35804947, 2022). "The TNT trial reported greater efficacy of a platinum than a taxane for BRCA1/2 PV carriers with metastatic hormone receptor (HR)–negative, HER2-negative (also known as triple-negative) breast cancer (TNBC)." (PMID 35723570, 2022). "Paradoxically, in BRCA1 and BRCA2 breast cancer tumors it seems that pCR does not serve as a surrogate marker of better clinical outcome and a higher pCR does not translate into improved disease-free and overall survival." (PMID 36580360, 2022). "BRCA1/2 PV carriers with HR-positive, HER2-negative breast cancer had twofold higher odds than noncarriers of receiving a platinum, as part of a more intensive chemotherapy regimen." (PMID 35723570, 2022). "This BRCA1-negative ADSCs were reported to induce a more aggressive phenotype in MDA-MB-231, that is already recognized as highly invasive breast cancer cell line." (PMID 34228231, 2021). "The effect of C/EBPβ on PARPi responsiveness was also observed in the HR-proficient breast cancer cell line MDA-MB-231, but not in the BRCA1-mutant MDA-MB-436." (PMID 33966038, 2021). "E.g. breast cancer is not subdivided according to the status of estrogen-receptor, progesterone-receptor, HER2 or BRCA1." (PMID 34174885, 2021).